ACE (angiotensin I converting enzyme)
Diseases named in the same sentence as ACE in open-access papers (continued):
Sharing a sentence is not in itself a finding about the gene and the disease.
Hypertension (continued). "Furthermore, hypertension is diagnosed when patients present a systolic and/or diastolic blood pressure greater than 130 mmHg and 85 mmHg, respectively, and/or specific treatment (angiotensin-converting enzyme (ACE) inhibitors, calcium channel blockers)." (PMID 26198245, 2015). "Therefore, inhibition of ACE activity is considered an effective approach to control hypertension." (PMID 25408464, 2015). "The most interesting points (other than the association between two rare causes of hypertension such as reninoma and bilateral MEN2B-related PHEO) are the persistence of detectable aldosterone levels in spite of bilateral adrenalectomy and the detection of ACE I/D polymorphism." (PMID 26084817, 2015). "However, no objective evidence demonstrated that hypertension after transplantation is associated with ACE I/D polymorphism." (PMID 26000752, 2015). "Natural food-based inhibitors that possess both renin- and ACE-inhibitory effects will usually be preferred as antihypertensive agents because this could provide more effective control of high BP, thus preventing hypertension." (PMID 26715103, 2015). "So we hypothesized that T2DM may be a result of complex interplay among polymorphism in ACE genes, hypertension, and obesity, even though in our previous study we were not able to correlate the ACE I/D polymorphism alone with the T2DM risk." (PMID 26491214, 2015). "Elucidating the pathophysiological mechanisms of ACE gene underlying OSAS susceptibility in connection with hypertension is beyond the capability of this meta-analysis, it is rational to speculate that the predictive role of ACE genetic alterations is manifested in the coexistence of hypertension." (PMID 26486181, 2015). "However, since these drugs were used by patients with hypertension (calcium channel blockers, ACE inhibitors) and stable angina (aspirin, ACE inhibitors) in all the study groups, their effect may be equally distributed." (PMID 26124907, 2015). "Thus, the ability of the cod peptides to inhibit both ACE and renin activities could be used as an effective tool to modulate the renin–angiotensin system in order to treat or prevent hypertension." (PMID 26715103, 2015). "The Hypertension in the Very Elderly Trial (HYVET), a randomized trial with hip fracture as a secondary outcome measure, revealed that treatment with a thiazide-like diuretic ± ACE inhibitor may reduce the risk of hip fracture." (PMID 26626043, 2015). "According to the Canadian Hypertension Education Program recommendations, calcium channel blockers provide more significant renal benefits than diuretics when combined with angiotensin-converting enzyme (ACE) inhibitors or angiotensin II receptor blockers (ARBs) in type 2 diabetes." (PMID 25918454, 2015). "The interest in bioactive peptides as agents for the control of hypertension continues to increase and our previous study has confirmed that rapeseed protein-derived peptides (Thr-Phe, Leu-Tyr and Arg-Ala-Leu-Pro) possess dual in vitro inhibitions of renin and ACE activities." (PMID 24603692, 2014). "Thus, the interaction between ACE I/D polymorphisms and hypertension was significant only in the nondiabetic nephropathy subgroup." (PMID 24498151, 2014). "Since our findings also revealed increased activation of RAAS, it is possible to speculate that the more severe hypertension observed in VDD+TDF could be explained by the increased mRNA expression of renin, AGT, ACE, and AT1a associated with augmented levels of aldosterone." (PMID 25048368, 2014). "It is hypothesized that disruption of tissue ACE/ACE2 balance results in changes in blood pressure, with increased ACE2 expression protecting against increased blood pressure, and ACE2 deficiency contributing to hypertension." (PMID 25009501, 2014).
Hypertension (continued). "Ethnicity [odds ratio (OR): 1.24; 95% confidence interval (CI): 1.08–1.42] and hypertension (OR: 1.55; 95% CI: 1.04–2.32) had significant moderate effects on the association between ACE I/D polymorphisms and CKD risk, but they were not significant in the diabetic nephropathy subgroup." (PMID 24498151, 2014). "In addition to the adverse effects of the prolonged use of ACE inhibitors as antihypertensive medication, the alternative ACE-independent, chymase-mediated conversion of AT-I to AT-II in certain organs presents further challenges for the management of hypertension." (PMID 25302619, 2014). "However, although ACE inhibitors such as captopril, enalapril and lisinopril are commonly used in the treatment of patients with hypertension, heart failure or diabetic nephropathies, they have significant undesirable side effects and safe alternatives are needed." (PMID 25364320, 2014). "While the Ang II infusion model is most reflective of secondary forms of hypertension, it should be noted that a major target of antihypertensive therapy in essential hypertension in humans has been directed toward limiting Ang II signaling (e.g., ACE inhibitors and angiotensin receptor blockers)." (PMID 25400581, 2014). "It is therefore not surprising that ACE variants have only a moderate effect on hypertension." (PMID 23469169, 2013). "Despite difficulties in study design and the assessment of environmental factors, future case-control studies may help to resolve these questions if the studies include information on the status of hypertension, the use of ACE inhibitors and environmental exposures, such as smoking history." (PMID 23826288, 2013). "However, Kabadou revealed that the ACE I/D polymorphism is not significant factor for hypertension in the Tunisian population." (PMID 24098401, 2013). "Unfortunately, widely studied experimental stimuli including pre- and post-conditioning may be impaired or negated with aging, relevant disease states such as diabetes, obesity and hypertension/hypertrophy, and commonly applied drugs such as ß-blockers and ACE inhibitors." (PMID 23991079, 2013). "In black adults requiring monotherapy for uncomplicated hypertension, drugs other than ACE-inhibitors may be preferred, though the proven benefits of ACE-inhibitors in some sub-groups and the large overlap of response between blacks and whites must be remembered." (PMID 24067062, 2013). "Furthermore, significantly more ACE inhibitors are prescribed after stroke in cohort 2; this might be because ACE inhibitors are known to very effective in the treatment of hypertension." (PMID 23734793, 2013). "However, studies simultaneously evaluating the effects of traditional risk factors including hypertension, dyslipidemia, and smoking on the association between the ACE genotypes and PAD are still lacking." (PMID 22144991, 2012). "Our data suggested that the 90 kDa ACE may be a marker for hypertension." (PMID 22666552, 2012). "In addition to GRK4, gene polymorphisms related to the renin-angiotensin-aldosterone system (RAAS), such as angiotensin converting enzyme (ACE), angiotensinogen (AGT), angiotensin II type 1 receptor (AGTR1), and aldosterone synthase (CYP11B2), have been reported to be associated with hypertension." (PMID 22518293, 2012). "Angiotensin I converting enzyme (ACE), a dipeptidylcarboxypeptidase, forms part of an enzymatic system essential to the modulation of blood pressure and is therefore implicated in related diseases, e.g., hypertension, chronic cardiac failure, cardiac infarctions and diabetic nephropathy." (PMID 22489144, 2012). "In addition to the classical hypertension and renal function candidate gene ACE, recent evidence suggests that several of these genes may play a role in the physiological control of renal function and blood pressure, even in the absence of drug treatment." (PMID 23049672, 2011).
Hypertension (continued). "Similarly to what is found for most blood pressure candidate genes in humans, results of associations between ACE variants and blood pressure and/or hypertension have been inconsistent, as illustrated by an absence of overall association in two meta-analyses." (PMID 23049672, 2011). "Australian, British, European and Canadian guidelines resulted in the lowest NNT for males and females; the highest NNT was for the risk blind initiation at diagnosis of statins and ACE inhibitors with no further management of hypertension or lipids (NNT = 14.4 for males and 11.7 for females)." (PMID 21283569, 2011). "Diabetic nephropathy is likely to manifest with comorbidities like hypertension, cardiomyopathy, and other microvascular complications, and these patients would be on multiple drug therapy which is high likely to include an angiotensin-converting enzyme (ACE) inhibitor/AT1 receptor blocker." (PMID 22235363, 2011). "In our study on hypertensive patients of Kashmir, we found that among 52 hypertensive cases the frequency of ACE DD genotype to be 46.15% (24/52), II 23.07% (12/52) and DI 30.77% (16/52) however no statistical significance was observed between the ACE gene I/D polymorphism and hypertension." (PMID 28352369, 2010). "Beta-blocker drugs along with ACE-inhibitors, calcium channel antagonists, imidazoline receptor antagonists, and diuretics are clinically well characterized for the therapeutic treatment of hypertension and are proven in reducing life-threatening cerebrovascular events." (PMID 21317458, 2010). "Therefore, the inhibition of ACE activity is a major target in the prevention of hypertension." (PMID 20479968, 2010). "We genotyped five polymorphisms of the AGT, ACE, AT1R, 5-HT2A, and 5-HTT genes in 245 patients with Hypertrophic Cardiomyopathy (HCM; 205 without an identified sarcomeric gene mutation), in 145 patients with LVH secondary to hypertension, and 300 healthy controls." (PMID 20594303, 2010). "Analyses of several clinical trials using antihypertensive agents in patients with and without hypertension have demonstrated that RAS blockade significantly reduces the risk of new-onset diabetes in patients treated with ACE inhibitors or ARBs, compared with diuretics, β-blockers, CCBs, or placebo." (PMID 19220522, 2009). "As the efficacy of these two types of antihypertensive medication is similar, it seems that ARBs might be prescribed to substitute for some ACE inhibitors in medical centers or regional hospitals and this trend probably was unrelated to the different severity of hypertension." (PMID 18559115, 2008). "Data from outcome studies show that several classes of drugs, including angiotensin-converting enzyme (ACE) inhibitors, angiotensin-receptor blockers (ARBs), beta-blockers, calcium channel blockers (CCBs) and thiazide-type diuretics, effectively lower BP and reduce the complications of hypertension." (PMID 18355239, 2008). "It is conceivable that many of the young individuals are at hypertension risk because of their ACE or AGT genotype, but have not yet shown hypertension at the time of genotyping, and may develop hypertension in their older age." (PMID 15642127, 2005). "Angiotensin I-converting enzyme (ACE, EC 3.4.15.1) inhibitors targeting the renin-angiotensin system (RAS) have been considered key medications for hypertension." (PMID 41596878, 2026). "Both ACE and DPP-IV are involved in diseases related to metabolic syndrome, such as hypertension or diabetes, and are clinically targeted for treatment." (PMID 40427700, 2025). "A history of hypertension was more common in CES than in ESUS (51.7% vs. 29.6%; p = 0.001), although the relative use of antihypertensive subclasses—including ACE inhibitors, ARBs, beta blockers, and calcium channel blockers—was comparable between groups." (PMID 41327082, 2025).
Hypertension (continued). "In the present study, the antihypertensive effects of LSE were associated with RAS inhibition, as evidenced by decreased plasma Ang II, ACE activity, and AT1R expression in L-NAME-induced hypertension following LSE treatment." (PMID 40872547, 2025). "For example, in a study using Bombyx mori species, products obtained by simulated gastrointestinal digestion showed high antioxidant activity and the ability to inhibit angiotensin-converting enzyme (ACE), a valuable property for the treatment of hypertension." (PMID 40565733, 2025). "Angiotensin-converting enzyme (ACE), a dipeptide carboxypeptidase, is a key target in the pathogenesis of hypertension and has significant implications for human health." (PMID 39856812, 2025). "Of particular interest is their inhibitory properties on ACE and DPPIV leading to a reduction in the severity of hypertension and diabetes." (PMID 40007962, 2025). "This study aimed to detect hypertension and non-dipping phenomenon in adolescents with T1D in a population of Serbia and to determine its relationship with clinical data and genetic risk factors, including various variants of the ACE and AGTR1 gene polymorphisms." (PMID 40149592, 2025). "Ang II can boost ACE levels while lowering ACE2 mRNA and protein in hypertension through the AT1R pathway that activates ERK/p38 MAP kinase (mitogen-activated protein kinase)." (PMID 41303587, 2025). "Note, antihypertensive agents including beta-blockers, calcium antagonists and angiotensin-converting enzyme (ACE) inhibitors and other drugs for the treatment of hypertension, were most frequently combined with lithium (n = 763, 27%)." (PMID 39945975, 2025). "This study aims to fill this critical gap by examining the impact of Humanin, MOTS-c, p66Shc, and ACE genotypes in the context of cardiovascular disease (CVD), hypertension (HT) and diabetes mellitus (DM)." (PMID 40367215, 2025). "Beyond their antioxidant capacity, many bioactive peptides function as Angiotensin-Converting Enzyme (ACE) inhibitors, helping regulate blood pressure and reduce hypertension-related risks." (PMID 41473198, 2025). "Their findings indicate that oilseed proteins, including those derived from rapeseed, are promising sources of peptides with ACE- and DPP-IV-inhibitory activities, underscoring their potential utility in the management of hypertension and diabetes." (PMID 40724272, 2025). "Notably, ACE inhibitors, commonly used for hypertension, may elevate cerebral Aβ levels." (PMID 40372199, 2025). "Typically, activation of the classic axis—angiotensin-converting enzyme (ACE)/ANG II/ANG II type 1 receptor (AT1R)—promotes vasoconstriction, oxidative stress, and inflammation, all of which contribute to hypertension." (PMID 39911806, 2025). "Angiotensin-converting enzyme (ACE) and dipeptidyl peptidase IV (DPP-IV) are integral to the pathogenesis of hypertension and type 2 diabetes mellitus, respectively." (PMID 40724272, 2025). "Overall, the findings of our study indicate that ginseng compounds, due to their significant ACE and CA-I inhibitory potential, favorable safety profiles, and promising pharmacokinetic properties, could serve as viable alternatives to synthetic drugs for hypertension treatment." (PMID 40430466, 2025). "Antihypertensive medications, including Angiotensin-Converting Enzyme (ACE) inhibitors, beta-blockers, and diuretics, are prescribed to manage hypertension." (PMID 40969606, 2025). "In patients with de novo hypertension (de novo HTN), the combination of HCTZ with ACE inhibitors (ACEI) or angiotensin II receptor blockers (ARB) also significantly lowered MAP." (PMID 40453665, 2025). "Given the involvement of AT1R in these processes, ACE inhibitors and AT1R blockers (ARBs) are widely used to control hypertension and prevent or delay the progression of cardiac remodelling and heart failure stemming from ang II overactivity." (PMID 40728970, 2025).
Hypertension (continued). "BK is vasoactive and a substrate of angiotensin-converting enzyme (ACE), the inhibitors of which are commonly used in the treatment of hypertension." (PMID 40572588, 2025). "Studies on diabetes and hypertension have investigated and reported on two important enzymes: dipeptidyl peptidase IV (DPP-IV) and angiotensin-converting enzyme (ACE)." (PMID 39942094, 2025). "These bioactive peptides have been shown to inhibit the activity of angiotensin converting enzyme (ACE), a component of the renin-angiotensin system that mediates systemic hypertension." (PMID 39013196, 2025). "Kolsi and collaborators demonstrated that an extract of C. nodosa has inhibitory effect in in vitro assays on the ACE enzymatic activity, with an IC50 value of 0.41 mg/mL, suggesting a possible role for a future application as a remedy for hypertension." (PMID 40218994, 2025). "The resulting hydrolysates exhibited enhanced antioxidant activity (3.9 ± 0.1 μmol TE/mg) and a strong ACE-inhibitory effect (IC50 = 0.052 mg/mL), confirming their potential as multifunctional ingredients for managing oxidative stress and hypertension." (PMID 41226263, 2025). "Sampatrilat (Compound 14, UK 81252) functions as a dual-action inhibitor targeting both ACE and NEP and it holds promise for therapeutic use in managing conditions such as hypertension and congestive heart failure." (PMID 39764460, 2024). "This study aimed to evaluate their anti-hypertensive potential through an in vitro inhibition assay of angiotensin-converting enzyme (ACE) and hypertension precursor enzymes and to assess the in vivo diuretic activity of HS." (PMID 38397511, 2024). "As we known, angiotensin receptor blockers (ARBs) and angiotensin-converting enzyme (ACE) inhibitors have been commended as the only agents for patients with CKD and hypertension." (PMID 40034487, 2024). "The classical RAS, comprising the ACE–angiotensin (Ang) II-AT1R axis, promotes vasoconstriction and contributes to hypertension." (PMID 39769369, 2024). "Antihypertensive peptides, particularly those that inhibit angiotensin-converting enzyme (ACE), hold significant importance in medical research, specifically in the context of cardiovascular disease treatment, particularly hypertension." (PMID 38352804, 2024). "Abnormal DNA methylation of BP-related genes, such as ACE and AT1R, contributes to hypertension by upregulating components of the RAS and hypomethylating their promoters." (PMID 39769369, 2024). "Using this data, we generated three L-subpopulations (LII, LID and LDD, namely one for each ACE genotype) and three H-subpopulations (HII, HID and HDD) of 100 virtual patients with arterial hypertension (see the generation algorithm in Materials and Methods)." (PMID 38707445, 2024). "In patients with CCD who also have hypertension, diabetes, LVEF ≤ 40%, or CKD, the use of ACE inhibitors, or ARBs for those intolerant to ACE inhibitors, is recommended." (PMID 38766996, 2024). "Generally, RAAS inhibitors, such as angiotensin-converting enzyme (ACE) inhibitors and angiotensin II receptor blockers (ARBs), are used to treat hypertension." (PMID 39650950, 2024). "Diverse medications, including diuretics, calcium channel blockers, angiotensin-converting enzyme (ACE) inhibitors, angiotensin II receptor blockers, beta blockers, and vasodilators, are currently available to control hypertension." (PMID 39770106, 2024). "While no single antihypertensive medication appears to be more effective at treating hypertension in patients with PAD, ACE inhibitors and ARBs should be considered first line as these confer the most cardiovascular benefits based on the current evidence." (PMID 39006738, 2024). "The angiotensin I-converting enzyme (ACE), a zinc-dependent dipeptidyl carboxypeptidase, is one of the main targets in treating hypertension, heart failure, myocardial infarction, and other related diseases." (PMID 39065005, 2024).